APC (APC regulator of Wnt signaling pathway)
Diseases named in the same sentence as APC in open-access papers (continued):
Sharing a sentence is not in itself a finding about the gene and the disease.
tumor (continued). "We grew organoids for a period of 5 months so that the initial single cell with only artificial APC intervention could naturally obtain mutations to transform into tumor cells." (PMID 34548081, 2021). "LDHA, β-catenin, and PCNA increased in the tumour tissues induced by injection of APC-mutated CRC cells expressing control shRNA and were significantly reduced in those generated by injection of the identical cells expressing PKM2 shRNA, as shown by IHC and western blot analyses." (PMID 33071283, 2021). "Notably, this tumor had both APC and BRAF mutations, which are generally exclusive, identified in separate subclones based on their prevalence." (PMID 34488871, 2021). "As such, a lower APC mutation frequency in metastases and a higher rate in the primary tumor may be linked to EMT of tumor CRC cells." (PMID 34707195, 2021). "The tumor 2 (NET G1, 10% tumor content) had mutations in APC p.S1315*(AF = 25.81%)." (PMID 34600484, 2021). "Furthermore, understanding the mechanisms underlying the generation of APC clusters – and possibly their destruction in CI‐resistant tumours – would be crucial in designing therapeutic interventions that foster anti‐tumour immunity." (PMID 33846997, 2021). "However, metabolic profiling of tissue samples can be confounded by the presence of other mutations in tumours, hence any metabolic differences cannot be directly attributed to the APC mutation." (PMID 33620068, 2021). "In the 27 tumor/germline matched cases 4 (15%) appeared as true somatic truncating APC mutations." (PMID 33500480, 2021). "However, the second germline mutation, c.3949G>C, which results in a glutamic acid to glutamine change at codon 1317 of APC (p.E1317Q), was accompanied by loss of the wild type allele in the tumour tissue." (PMID 33352971, 2020). "In the tumor biallelic, inactivating APC variants were identified." (PMID 31598872, 2020). "Finally, we assessed the tumor‐preventive efficacy of aspirin treatment in APCMin/+ mice which carry a missense mutation in one allele of the tumor suppressor gene APC." (PMID 31994315, 2020). "First, inhibitory signaling via LAG‐3 is transmitted by its cytoplasmic KIEELE domain when the receptor binds with high affinity to MHC class II,161 highlighting the potential for both tumor‐associated APC and MHC class II‐expressing cancer cells to suppress T cell function via this pathway." (PMID 32508018, 2020). "Twelve tumours had a single APC mutation while six tumours had two mutations." (PMID 33352971, 2020). "The occurrence, type, and location of APC mutations are reported, as is evidence of microsatellite instability, loss of heterozygosity, and APC promoter methylation, and these findings are compared to clinical features of the tumours." (PMID 33352971, 2020). "Furthermore, loss of ERβ results in pro-inflammatory environment and increased tumor development in both APC Min/+ and colitis-associated tumor mouse model." (PMID 32999402, 2020). "Gene SLC3A2 and APC, which were associated with metastasis and neoplasia, were included." (PMID 33425983, 2020). "Altogether, it appears that loss of MACROD2 as such is not sufficient to drive tumourigenesis, but may have an additive effect in models prone to tumour formation such as loss of APC in colorectal cells." (PMID 32151005, 2020). "Likewise, colon tumors, which express high MYC levels because of loss-of-function mutations in the APC tumor suppressor gene, depend on NUAK1 for tumor growth and maintenance." (PMID 32006464, 2020). "Mutations in the APC gene that occur in the development of CRC are drivers of tumor growth." (PMID 32079164, 2020). "Mutations in the APC tumour suppressor are a major driver of sporadic colorectal cancers, where it could be shown that even haploinsufficiency of MACROD2 leads to more and larger adenoma formation." (PMID 32151005, 2020).
tumor (continued). "Importantly, tumors derived from Villin-CreERT2, Usp22flox mice containing a mutation in the Adenomatous Polyposis Coli (APC) tumor suppressor gene (APC1638N/+) similarly displayed decreased HSP90AB1 levels compared to the Usp22 wild type control tumors." (PMID 31801945, 2019). "Germinal and somatic mutations in the adenomatous polyposis coli (APC) gene, a key tumour suppressor, have been identified to be the root cause for FAP, a condition that predisposes a person to develop numerous, typically hundreds of adenomatous polyps in the bowels, specifically the large bowel." (PMID 31870096, 2019). "Some authors suggested that the APC mutation has a relevant role in providing a selective advantage, through the activation of the Wnt signal transduction pathway and the chromosomal instability in the tumor cell." (PMID 31142796, 2019). "Importantly, proof of concept studies has shown that restoration of APC in aggressive carcinoma of mice causes tumour regression." (PMID 30760720, 2019). "Increased COX-2 transcription or mRNA stability due to the oncogenic RAS and the loss of function of the APC tumor suppressor gene may occur via signal transduction pathway of Wnt/APC, RAS signaling, ERK, p38 MAPK, and AKT/PKB (protein kinase B)." (PMID 31108984, 2019). "For prognostication, pre- and posttherapeutic analyses alike of KRAS and APC mutations provided information on tumor load (quantitative analysis) and allowed molecular profiling (qualitative analysis) to guide treatment decisions by determining the indication for (neo-)adjuvant therapies." (PMID 32328554, 2019). "The possible reason for lower APC mutation frequency in TNM III+IV tumor could be due to complementary mechanisms like PEG3, which has been reported to inhibit Wnt signaling by degrading β-catenin." (PMID 29937994, 2018). "APC encodes a tumor suppressor protein that negatively regulates the Wnt signaling pathway." (PMID 29976158, 2018). "Interestingly, deletion of CDX2, the intestinal transcription factor responsible for GUCY2C expression, similarly potentiates tumor burden, chromosomal aberrations, and APC loss of heterozygosity." (PMID 30131940, 2018). "This mislocalization could explain the profound effect of Ctbp2 haploinsufficiency on polyp number and survival in Apcmin mice and supports further therapeutic development of CtBP as a target in APC mutated neoplasia." (PMID 30197752, 2018). "Another possible reason of decreased mutation frequency of APC and Wnt signaling in lymph node positive cancer may due to tumor cell eradication by immune cell, if these mutated genes are not essential for CRC maintenance." (PMID 29937994, 2018). "Each dot means a tumor patient with a somatic mutation in APC hotspots." (PMID 29697365, 2018).
tumor (continued). "Together, these findings demonstrate that the Drosophila adult digestive tract recapitulates key events in both the initiation and progression of tumorigenesis following APC loss, and also offers a promising platform for both drug screening and the identification of novel tumor modifiers." (PMID 29615557, 2018). "Recently it has been reported that a new Xenopus tumour model might be especially useful for identifying or characterising modifier genes associated with APC mediated tumour formation." (PMID 28331556, 2017). "Importantly, USP7 inhibition does not affect normal cells with WT APC, indicating that USP7 can be used as a tumor-specific drug target for APC-mutated CRCs." (PMID 29045831, 2017). "Finally, the Wnt-activating role of USP7 is specific to APC mutations; thus, it can be used as a tumor-specific therapeutic target for most CRCs." (PMID 29045831, 2017). "Importantly, we also established that the second APC allele was inactivated by a point mutation, and that this tumor had stable microsatellites, indicating that faulty DNA repair did not initiate tumorigenesis in this case." (PMID 28561751, 2017). "Thus, the in vivo data reveal that PrxII promotes the survival of tumor cells in the intestinal adenomatous polyposis driven by APC mutation." (PMID 28659575, 2017). "It is important to note that the APC mutation is the first mutation in the majority of CRCs, but the precise order of the subsequent mutations may vary from tumor to tumor." (PMID 26539643, 2016). "Second, a secondary WNT pathway gene mutation might contribute to tumorigenicity in remaining single APC-mutated tumours." (PMID 27302369, 2016). "We examined whether methylation of APC in tumor DNA was associated with patient clinicopathological features in both cohorts." (PMID 26884349, 2016). "In tumor and liver metastases tissues, β-catenin revealed heterogeneous sub-localizations, highlighting that different mechanisms, other than β-catenin or APC gene mutations, could control this shift." (PMID 27765918, 2016). "An analysis of the TCGA CRCs, whose whole-exome-sequencing data allowed us to examine WNT pathway genes more comprehensively, did identify a substantial number of APCwt (∼53%), one-hit (∼33%) or two-hit (∼30%) APC tumours, which had one or more non-APC WNT pathway gene mutations." (PMID 27302369, 2016). "Truncation of the APC protein results in the loss of tumor suppression." (PMID 26863299, 2016). "Moreover, APC two-mutation- and zero-mutation tumours showed worse survival compared with APC one mutation tumours (log-rank P=0.018)." (PMID 27302369, 2016). "Collectively, we have identified a significant number of tumours harbouring one-hit APC mutations, many of which retained WNT activation that could not be explained by a few possible ‘second-hit' mechanisms." (PMID 27302369, 2016). "In this Taiwanese population, the frequency of APC mutations in tumor tissues was 42.4%." (PMID 27578919, 2016). "Therefore, it was postulated that mutations in APC lead to chromosomal instability and induce aberrant Wnt signaling, thus contributing to tumor progression." (PMID 27898031, 2016).
tumor (continued). "Many studies have focused on APC hypermethylation, which might cause APC downregulation and has been associated with clinicopathological features of tumor aggressiveness." (PMID 27898031, 2016). "The loss of APC function leads to translocation of β-catenin from the lateral cell membrane to the nucleus, where it promotes transcription of multiple genes involved in tumour growth and invasion." (PMID 28105931, 2016). "Therefore, APC gene mutation can directly influence the function of Wnt signal pathway and the interaction between Gsk 3β and β-catine to take part in the tumor occurrence." (PMID 27065015, 2016). "Among APC-mutated tumours, 38% (118/312) displayed two or more truncating mutations." (PMID 27302369, 2016). "A second mutation in the APC tumor suppressor was identified (c.2368A > T, p.R790*) in the tumor." (PMID 27799065, 2016). "Whether the specific APC mutation prompts different desmoid tumor surveillance techniques and schedules in certain groups of patients has not been previously determined." (PMID 26179480, 2015). "One obvious difference is in sporadic human CRC, tumours develop over a number of years and the sequential mutations in APC may provide different selective benefits and other functions of APC may be very important in human carcinogenesis." (PMID 26240067, 2015). "Interestingly, mutations of the APC gene in rats induces localized tumour development within the colon and rectum, an observation that differs from mice whereby tumour development is generally restricted to the small intestine." (PMID 26561503, 2015). "Thus, dysregulation of these processes by mutations in the APC gene is frequently implicated in tumor initiation and progression." (PMID 25406066, 2014). "Moreover, even in tumor cells with APC mutations, β-Catenin dependent transcription and expression of WNT target genes was compromised when blocking PI3K and this effect seems to be mediated by impaired binding of β-Catenin to its target gene promoters." (PMID 24930890, 2014). "However, it does appear that for those tumours with the c.3924_3925insA and APC LOH, the c.3924_3925insA is on the mutated allele and LOH involves the wild-type allele." (PMID 24416237, 2014). "For the following results we ignore missense and silent APC mutations found in six tumours." (PMID 24416237, 2014). "For CDKN2A and APC, the mutation proportions were initially (in tumor samples) strongly shifted towards nonsense homozygous; however, the increase of this mutational type with the subsequent decrease of the other types of mutations was statistically significant." (PMID 25119593, 2014). "Thus, the KAD rat pinpoints a function of APC in the regulation of inflamed colonic states, separate from the tumor-suppressing functions encoded proximally to the C-terminus." (PMID 25288683, 2014).
tumor (continued). "However, since APC is commonly mutated and/or truncated in tumor cells, the role of APC in regulating microtubule plus-ends is most likely independent of Wnt signaling." (PMID 23825799, 2013). "To do so, we investigated the possibility that CDON inactivation in mice may affect tumour progression by analyzing the effect of the CDON mutation on adenocarcinoma (ADK) formation in an APC+/1638N genetic background." (PMID 23940460, 2013). "This “β-catenin paradox” nicely illustrates how intra-tumour heterogeneity and possibly tumour stemness ensue at the very initial stages of the adenoma-carcinoma sequence and lead to different Wnt signalling levels among different tumour cells lineages sharing the same (APC) mutations." (PMID 24069241, 2013). "Previous reports have shown that IWP-4 and XAV-939 are effective in cells which have loss of APC tumor suppressor function, and this effectiveness could be explained by the rate-limiting role that Axin proteins play in canonical Wnt pathway." (PMID 24188694, 2013). "For example, if APC is mutated or down-regulated after tumor cell extravasation, it may actually promote tumor cell colonization by promoting cell-cell or cell-matrix interactions." (PMID 23302090, 2013). "In particular, RASSF1A, together with APC, may be a good prognostic factor for tumor reappearance; moreover, patients with methylated APC or RASSF1A coding genes were also significantly associated with shorter recurrence-free survival." (PMID 23372425, 2012). "When mutated, the tumor suppressor gene, APC, is associated with chromosome instability and tumor progression via beta-catenin signaling, and when normally expressed is a critical component of cellular defense mechanisms involving cell cycle arrest, DNA damage, and repair or by inducing apoptosis." (PMID 22737227, 2012). "Actually, the “just right signalling” hypothesis for which experimental support has been recently provided states that APC truncating mutations are selected to avoid too much β-catenin signalling that would be detrimental to tumour development." (PMID 22509309, 2012). "To molecularly characterize canine CRC, we investigated exonic sequence mutations of adenomatous polyposis coli (APC), the best known tumor suppressor gene of human CRC, in 23 sporadic canine colorectal tumors, including 8 adenomas and 15 adenocarcinomas, via exon-resequencing analysis." (PMID 23251390, 2012). "In this strain, an increased tumor incidence and tumor size is observed, consistent with the in vitro data obtained in human cancer cell lines: PPARγ ligands inhibit cell growth even in the presence of APC mutations." (PMID 22848209, 2012). "Of 63 informative tumours with the APC gene mutated, 28 had LOH at the APC locus (44.4%)." (PMID 21901162, 2011). "We propose several mechanisms by which cancer-related missense mutations in the large disordered domain of APC may interfere with tumor suppressor activity." (PMID 21859464, 2011). "In animal models the APC truncation mutant APC1–1638 increases tumor susceptibility." (PMID 21311754, 2011). "These tumours may have mutations in other genes such as AXIN or APC that lead to abnormal β-catenin accumulation or activation through a different pathway." (PMID 21992464, 2011). "Inactivation of both APC alleles (APC-/-) is considered necessary for tumor formation." (PMID 22168384, 2011). "Significantly increased LOH in our tumours with just 1 somatic APC mutation, the trans position of 2 pathogenic APC mutations confirmed in tumours where the mutation phase was tested, and preferential loss of the wildtype allele in tumours with LOH and an APC mutation support the two-hit model." (PMID 21901162, 2011).